ANKRD34C (ankyrin repeat domain 34C)
Tractability: PROTAC: its protein half-life has been measured.
Gene: Protein-coding gene on chromosome 15 (79,282,722 to 79,298,239, forward strand). Ensembl gene ENSG00000235711.
Subcellular location (Human Protein Atlas): Mitochondria
Gene Ontology:
Cellular component: pi-body
Genetic constraint (gnomAD): Loss-of-function variants: 1 observed, 1.92 expected, observed/expected ratio (o/e) 0.52, 90% interval 0.17 to 1.76. That is too few expected variants to judge how well the gene tolerates losing a copy. Missense variants: 559 observed, 677.17 expected, observed/expected ratio (o/e) 0.83, 90% interval 0.77 to 0.88. Synonymous variants: 258 observed, 265.83 expected, observed/expected ratio (o/e) 0.97, 90% interval 0.88 to 1.08.
Homologues: Orthologues: chimpanzee ANKRD34C (99% identical), macaque ANKRD34C (97% identical), pig ANKRD34C (92% identical), rat Ankrd34c (91% identical), mouse Ankrd34c (90% identical), dog ANKRD34C (88% identical), rabbit ANKRD34C (86% identical). Paralogues in human: ASZ1 (15% identical).
Diseases named in the same sentence as ANKRD34C in open-access papers:
ANKRD34C is named in the same sentence as 1 disease in open-access papers, as found by Europe PMC text mining. Sharing a sentence is not in itself a finding about the gene and the disease.
ANKRD34C shares sentences with these, for which no sentence is quoted: infection (1 paper).